CD4 (CD4 molecule)
Diseases named in the same sentence as CD4 in open-access papers (continued):
Sharing a sentence is not in itself a finding about the gene and the disease.
hepatocellular carcinoma (continued). "In the current study, we showed distinct changes of BTLA and HVEM expressions on peripheral blood CD4+ and CD8+ T cells in patients with hepatocellular carcinoma (HCC); BTLA expression were significantly upregulated on circulating CD4+ but not CD8+ T cells." (PMID 30116751, 2018). "Therefore, defects in senescence surveillance performed by CD4+T cells as well as by macrophages, could result in the development of murine hepatocellular carcinomas, which provides another mechanism governing how CD4+T cells affect NASH–HCC transition." (PMID 39000005, 2024). "In hepatocellular carcinoma (HCC) cases, the expression level of BTLA markedly increases in circulating CD4+ cells rather than in CD8+ T cells." (PMID 33859648, 2021). "In human breast cancers and hepatitis B virus positive hepatocellular carcinomas (HCC), very low TCR repertoire overlap between TI-Tregs and conventional T-cells suggests little to no conversion of conventional CD4+ T-cells into Tregs." (PMID 29887862, 2018). "We report a case of a 66-year-old man with a history of HCV related cirrhosis (HCV) and hepatocellular carcinoma (HCC) who was found to have PML in the setting of a negative viral load in the CSF and a CD4+ >200." (PMID 27529042, 2016).
cervical carcinoma (218 papers, 2005 to 2026). A carcinoma arising from either the exocervical squamous epithelium or the endocervical glandular epithelium. "A higher ratio of CD8+ TILs to CD4+ Tregs is associated with better survival rates in cervical cancer (5-year survival rate: 82% vs. 44%)." (PMID 39888529, 2025). "We and others found lower CD4 cell counts to be associated with an increased risk of cervical dysplasia and cervical cancer." (PMID 41216952, 2025). "The decreased CD4/CD8 ratio was significantly associated with the poorer prognosis of patients with cervical carcinoma and patients with nasopharyngeal carcinoma." (PMID 41225509, 2025). "In contrast, CD4+ T cell in cervical cancer are generally associated with immunosuppressive functions, though their roles remain controversial." (PMID 40539072, 2025). "The risk of cervical cancer has been shown to be 10 times more in severely immunocompromised patients (with a CD4 cell count less than 200/μL) than those with a CD4 cell count of 200/μL and above." (PMID 35432696, 2022). "Through ex vivo flow cytometric data obtained prior to clinical interventions of all the patients in the cohort, we have also investigated if the CD8+/CD4+ TIL ratio is a risk factor for cervical cancer." (PMID 34150643, 2021). "A recent South African study found associations between lower CD4 cell counts and an increased risk of Kaposi sarcoma, cervical cancer, non-Hodgkin lymphoma and Hodgkin lymphoma." (PMID 34886257, 2021). "Being older than 50 and having a low CD4 count at the time of cART initiation, were risk factors for invasive cervical cancer development." (PMID 34301269, 2021). "Activated CD4 memory cells were associated with favorable outcomes in patients with cervical cancer and favorable outcomes after radiotherapy in patients with multiple cancers." (PMID 34277706, 2021). "Instead, a few studies reported that the decreased cell number of CD4+ T cells was associated with worse long-term survival rates of cervical cancer patients." (PMID 34553029, 2021). "When markedly immune-suppressed (i.e., CD4+ cell count <200 cells/ul), the risk for cervical cancer is 8-fold higher in women living with HIV compared to HIV-negative women." (PMID 34277540, 2021). "A previous study showed that decreased proportions of tumor-infiltrating CD4+ T cells and a reversed CD4+/CD8+ cell ratio were significantly associated with the clinical outcome of patients with cervical cancer." (PMID 32131750, 2020). "Educational status, duration of HIV diagnosis, partner support, knowledge status about risk factor, CD4 count and attitude towards cervical cancer and its screening were associated with cervical cancer screening utilization." (PMID 31744548, 2019). "Multiple doses of HPV vaccines are effective in providing protection against HPV-associated cervical cancer by inducing CD4+ and CD8+ T cell immune responses for several years." (PMID 30875953, 2019). "Of crucial importance, ART is associated with a reduction in incidence of invasive cervical cancer, especially if started at higher nadir CD4 cell count, and used over longer durations by adherent patients." (PMID 29107561, 2018). "Cervical intraepithelial neoplasia, a premalignant abnormal growth preceding cervical cancer, is negatively associated with the presence of circulating cytotoxic CD4 T cells." (PMID 28167943, 2017). "The aim of our study is to examine the expression of HLA-I, CD8 and CD4 in various cervical diseases and investigate their association with cervical cancer." (PMID 29147220, 2011). "A decreased CD4+/CD8+ ratio is commonly associated with poor prognosis in cervical cancer, with studies showing that patients with CSCC who have a low CD4+/CD8+ ratio exhibit worse five-year survival rates, higher lymph node metastasis rates and faster tumor growth." (PMID 40539072, 2025).
cervical carcinoma (continued). "Importantly, RH for cervical cancer has been reported to decrease CD4+ T cell and NK cell numbers and the CD4+/CD8+ ratio, indicating that surgery can cause immune dysregulation." (PMID 32309426, 2020). "Notably, after a cervical cancer diagnosis only lower CD4+ T-cell count was associated with decreased survival rates." (PMID 24760049, 2014). "This is contrary to other study findings in which a low CD4+ count was associated with advanced cervical cancer stages at presentation.The difference may be attributed to the small sample size in our study." (PMID 22862747, 2012). "Further CIBERSORT and MCP-counter analysis showed that CD8+ T cells, activated memory CD4+ T cells, T cells follicular helper, Cytotoxic lymphocytes, B lineage, and Myeloid dendritic cells were having a higher fraction in low-risk patients with cervical cancer." (PMID 35657977, 2022). "It has been observed that a reduction in the number of CD4+ lymphocytes in patients with breast and cervical cancer may be associated with faster tumour growth and lymph node infiltration, but, on the other hand, high levels of CD4+ T lymphocytes can reduce the risk of tumour." (PMID 35743468, 2022). "Thus, the results from our in situ analysis indicated that the proportions of Th17 within CD4+ or IL‐17+ cells might be linked to enhanced activation of AKT signaling pathway during cervical cancer progression." (PMID 34469022, 2021). "Numerous registry formats must be completed, and several patient investigations, such as CD4 testing, viral load monitoring, and cervical cancer screening, are required." (PMID 41557672, 2026). "In parallel, global abundance proteomics and phosphoproteomics of cervical cancer cells exposed to HIV-1-infected human primary CD4+ T cell secretomes revealed altered MAPK, PI3K-AKT, cell cycle, and beta-catenin pathways." (PMID 42305618, 2026). "Lowest CD4 count over 30 months was the most informative measure for cervical dysplasia while CD4 count lagged by 24 months was most informative for cervical cancer." (PMID 41689274, 2026). "In cervical cancer, CD4+ T cells exhibit impaired responses to HPV peptides, contributing to tumor immune tolerance." (PMID 40264780, 2025). "HPV-induced cervical diseases, including CIN and cervical cancer, are linked to weak HPV-specific CD4+ and CD8+ T-cell responses.Impaired systemic or vaginal immunity can disrupt the balance of CD4+ and CD8+ T cells." (PMID 41142594, 2025). "We detected that LSP1 was positively associated with both CD4+ and CT8+ T cell abundance in HPV16-positive cervical cancer." (PMID 40038352, 2025). "Taken together, these data confirm that MUC1 secreted by tumor cells interacts with SIGLEC9 on CD4+ T-cells in the tumor microenvironment of cervical cancer." (PMID 41418390, 2025). "Compared to the precancerous stage, the ratio of CD4+/CD8+ T cells in the TME of cervical cancer patients is significantly increased, with CD4+ T cells gradually becoming more predominant in the immune microenvironment." (PMID 40539072, 2025). "The population of CD4+ Th cells comprise heterogeneous subgroups and some authors reported different roles of these subgroups in cervical cancer." (PMID 41007768, 2025). "Cervical cancer rates decreased with increasing CD4 cell counts (per 100 cells/μL increase; aHR 0.77; 95% CI 0.60–0.98)." (PMID 41216952, 2025). "High-risk types are associated with intraepithelial neoplasia and cancers of the cervix, anus, and penis, especially in PLWH with low CD4+ counts." (PMID 41295583, 2025). "In a recent study, patients with cervical cancer who had higher levels of infiltration of naïve CD4+ T cells had a worse prognosis, but higher levels of M0 macrophage infiltration was associated with tumor stage and a better prognosis." (PMID 38746677, 2024). "According to a study, activated memory CD4+ T cells and mast cells were independent predictors of overall survival for patients with cervical cancer." (PMID 38746677, 2024).
cervical carcinoma (continued). "Here, our results showed that the HPV oncogenes were able to increase those cell numbers in the same way as observed in the CD4+ T cell infiltration in cervical cancer." (PMID 39599846, 2024). "A significant increase in Treg frequency expressed as FoxP3 + Tcells as a proportion of CD4 + CD25 + cells was recorded in women with cervical cancer (11.00 ± 19.79%) compared to the controls (1.71 ± 8.91%), (p < 0.0001)." (PMID 37670247, 2023). "We report a significant increase in the frequency of CD4 + CD25 + FoxP3 + T cells (Tregs) in the peripheral blood of cervical cancer participants." (PMID 37670247, 2023). "Overall, in women living with HIV and having a CD4 count > 350, Treg frequency was significantly greater in cervical cancer than in controls, p = 0.0077 (Mann-Whitney)." (PMID 37670247, 2023). "Logistic regression analysis was applied to our data to assess the association of cervical cancer with Tregs and other variables (Age, HIV, CD4, HPV genotype, STI, loss of weight and smoking)." (PMID 37670247, 2023). "Infiltrating CD3 + and CD4 + T-cells have a positive effect on cervical cancer prognosis, whereas regulatory T-cells infiltration increases with cervical lesion progression." (PMID 37101242, 2023). "Tumor-infiltrating CD4+ T cells and reversed CD4/CD8 ratios have been significantly associated with LNM in cervical cancer, indicating higher levels of lymphocytes and blood platelets, which aligns with our findings." (PMID 37655103, 2023). "In most other studies, about 60–80 % of HIV-positive patients were on ART at cervical cancer diagnosis, and CD4 cell counts were generally lower (<400 cells/μL)." (PMID 36185101, 2022). "In another aspect, rapid tumor growth and lymph node metastasis are closely related to the reversion of the CD4+/CD8+ ratio and the reduced proportion of tumor-infiltrating CD4+ T cells in patients with cervical cancer." (PMID 36408157, 2022). "One study from South Africa found that advanced age, but not CD4 count, was associated with a higher rate of invasive cervical cancer among women living with HIV; but another found that CD4 count was associated with abnormal cervical smear results." (PMID 35077501, 2022). "TILs were also shown to have a beneficial effect in advanced cervical carcinoma as distinct infiltration of CD3+, CD4+, CD8+, CD206+ and FOXP3+ TILs were significantly associated with progression-free and overall survival in cervical cancer." (PMID 36612258, 2022). "Univariate Cox regression analysis showed that activated B cell, activated CD8 T cell, eosinophil, monocyte, activated CD4 T cell, effector memory CD8 T cell, immature B cell, and plasmacytoid dendritic cell were strongly associated with OS of cervical cancer." (PMID 35651784, 2022). "Meanwhile, decreased proportions of tumor-infiltrating CD4+T cells were found to be closely related to tumor progression and lymph node metastasis in cervical carcinoma." (PMID 35570842, 2022). "Current empirical evidence suggests that HIV treatment does not completely eliminate the excess HPV-related disease progression and cervical cancer risk associated with HIV, and that it depends on CD4 at initiation and duration on ART." (PMID 36583170, 2022). "In this study, monitoring of cervical cancer patients during cervical cancer therapy showed a decrease in CD4+ T cells in the patients` blood, but a significant increase in Th17 frequencies after aCRT and pCRT in comparison to patients with surgery alone." (PMID 34469022, 2021). "It would be clinically relevant if the HPV VLs, cervical cytology, and CD4 counts are considered into cervical cancer screening programs for triage and follow-up of these women." (PMID 36303978, 2021). "In contrast to CD4+ T cells, frequencies of Th17 cells were significantly increased during cervical cancer therapy." (PMID 34469022, 2021).
cervical carcinoma (continued). "The purpose of the study was to investigate the accuracy of HPV genotype testing in isolation and in combination with CD4 and HIV viral load (VL) for the identification of women infected with HIV at risk for developing cervical cancer." (PMID 33605553, 2021). "CCL20 is also predominantly expressed in the stroma of cervical cancer tissue and correlates with stromal infiltration of CD4+IL17+ cells and with advancing International Federation of Gynecology and Obstetrics (FIGO) stage." (PMID 32707869, 2020). "With regard to cervical cancer, previous research has revealed changes in T cell subsets and NK cell populations as well as inhibition of NK cell activity by CD4+ regulatory T cells." (PMID 32309426, 2020). "Colleagues from France characterized T cells (CD4+, CD8+, CD45 RO+) by immunohistochemistry in high-risk HPV-infected cervical cancers and premalignant lesions." (PMID 32131750, 2020). "To find the relationship between tumor-related CD4+ T cells and clinicopathological features of cervical cancer, we designed our experiment." (PMID 32552719, 2020). "Consistent with our findings, a previous investigation reported that RH for cervical cancer reduced CD4+ T cell and NK cell numbers." (PMID 32309426, 2020). "In our previous work (a manuscript published in Chinese), we evaluated CD4+CD25highCD127low regulatory T cells in the peripheral blood of cervical cancer and precursor lesion patients." (PMID 32131750, 2020). "In contrast, the percentage of CD8+ T cells found in cervical carcinomas was similar to that in normal cervical tissues, although the composition of CD4+ T cells did differ." (PMID 32927747, 2020). "An increased frequency of cervical cancer screening visits remains important especially among women on ART if they have started at a low nadir CD4 cell count." (PMID 29107561, 2018). "Educational status, parity, number of years after being diagnosed as HIV positive, and CD4 count were predictors of cervical cancer screening." (PMID 29879969, 2018). "Educational status, parity, length of time after diagnosis as HIV positive, and CD4 count are important predictors of cervical cancer screening." (PMID 29879969, 2018). "In this study, factors significantly associated with the uptake of cervical cancer screening among HIV positive women were educational status, parity, length of time since HIV was diagnosed, and recent CD4 cell count." (PMID 29879969, 2018). "Our results indicate that women on ART had a lower prevalence of high-risk HPV and a reduction in the incidence of histology diagnosed HSIL-CIN2+ and invasive cervical cancer, after adjustment for CD4 cell count and treatment duration." (PMID 29107561, 2018). "The number and functional orientation of tumor-infiltrating CD4+ and CD8+ T cells and the presence of M1 type macrophages are strongly associated with survival in patients with cervical cancer after primary treatment." (PMID 28344877, 2017). "More recent service developments have been the introduction of point-of-care CD4 counts (2011), and family planning and cervical cancer screening (2012) and these have become the standard of care." (PMID 28793895, 2017). "In a previous study in cervical cancer patients, elevated PD-1 expression on CD4+ T cells was demonstrated after CCRT33." (PMID 28900290, 2017). "Although this merits further investigation, it is in concordance with the observation that it is the high CD4/CD8 ratio of tumor-infiltrating lymphocytes (TILs) and thus a low CD8 count, that is linked to improved survival of patients with cervical cancer." (PMID 28659181, 2017). "In the present study, we demonstrate that human cervical cancer (CxCa) and tumour-infiltrating Treg cells (CD4+CD25hiCD127low cells) contain elevated levels of hormone E2 which is in complex with ERα in the latter." (PMID 29229929, 2017).